RETN (resistin)
Diseases named in the same sentence as RETN in open-access papers (continued):
Sharing a sentence is not in itself a finding about the gene and the disease.
Sepsis (continued). "The levels of resistin were higher in sCAP patients compared to uCAP patients, which is in line with the observation that sepsis patients also have elevated levels of resistin." (PMID 37342494, 2023). "Results revealed a negative correlation between neutrophils and CD247, CD2, and KLRB1, and a positive correlation with RETN in both COVID-19 and sepsis." (PMID 37822934, 2023). "Our research highlights the particular and protective function of resistin in preventing sepsis-related death." (PMID 37834432, 2023). "Accordingly, GYG1 and RETN were identified as candidate biomarkers for the diagnosis of sepsis in VLBW infants." (PMID 37139640, 2023). "We also identified three methylation CpG sites, located in RETN or its promoter region—cg06633066, cg22322184, and cg02346997—that directly affected both resistin protein levels and sepsis death in the ICU." (PMID 37834432, 2023). "One of these studies compared resistin levels between COVID-19 and sepsis patients, and showed increased levels in the latter group." (PMID 37238973, 2023). "This study aimed to explore the differentially expressed genes (DEGs) specific to cell types in sepsis and investigate the role of resistin in the survival of sepsis patients through Mendelian randomization (MR) analyses." (PMID 37834432, 2023). "In summary, our study’s MR analyses provide support for a protective effect of resistin in sepsis and indicate potential for drug development." (PMID 37834432, 2023). "The primary goal of this study was to establish a reproducible in vivo model with which to investigate the effect of human resistin on sepsis severity and organ dysfunction." (PMID 35286340, 2022). "At 6 h following sepsis, the number of circulating neutrophils (P = 0.0063) and antigen-presenting neutrophils (P = 0.0052) was significantly lower in mice producing resistin." (PMID 35286340, 2022). "Since this initial report, certain studies have confirmed the value of resistin as a biomarker of sepsis severity while others have suggested a more direct relationship between blood resistin concentration, endothelial markers and organ failure." (PMID 35286340, 2022). "In the Osaka cohort 2, plasma resistin levels were elevated in COVID-19 and sepsis patients compared to controls at all measurement points and were associated with inflammatory cytokines and endothelial cell adhesion molecules." (PMID 35784283, 2022). "We anticipated that sepsis-induced increases in human resistin would exacerbate the hypothermia, organ dysfunction and mortality in mice producing this cytokine, validating the translational relevance of our model." (PMID 35286340, 2022). "Several mechanisms of resistin secretion in sepsis have been reported, but the mechanism in COVID-19 has remained unclear." (PMID 35784283, 2022). "A recent study used single cell RNA sequencing to reveal a CD14+ monocyte phenotype named MS1, characterized by high expression of RETN, ALOX5AP, and IL1R2, that was unique in patients with sepsis and associated with sepsis-induced immunosuppression." (PMID 36470832, 2022). "Because of the strong correlation between the blood concentration of circulating resistin and the illness severity of septic patients, resistin has been proposed as a mediator of sepsis pathophysiology." (PMID 35286340, 2022). "In the present study, the resistin level in sepsis, as well as those of the cytokines, was higher than that in COVID-19." (PMID 35784283, 2022). "Correlations among resistin, inflammatory cytokines and endothelial cell adhesion molecules were evaluated in COVID-19 and sepsis." (PMID 35784283, 2022). "We evaluated 8 cytokines and 8 adipocytokines in both sepsis and burns and concluded that resistin forms a network with IL-6, IL-8, IL-10 and MCP-1 by hierarchical clustering analysis based on Spearman correlation." (PMID 35784283, 2022).
Sepsis (continued). "Second, to understand pathogenesis, we evaluate resistin, cytokines and endothelial cell adhesion molecules in COVID-19 compared with sepsis." (PMID 35784283, 2022). "The genes overexpressed in ARDS were often found to be associated with a more severe sepsis outcome in other studies (including MMP8, RETN, and OLFM4)." (PMID 33692779, 2021). "In recent years, PCT, interleukin-6 (IL-6), HBP, C-reactive protein (CRP), serum resistin, and other indicators have been used clinically to assess the severity and prognosis of sepsis." (PMID 34514164, 2021). "Currently, procalcitonin (PCT), interleukin-6 (IL-6), heparin-binding protein (HBP), C-reactive protein (CRP), serum resistin, and other indicators can be used to assess the severity and prognosis of sepsis." (PMID 34514164, 2021). "Further, recent experimental data have highlighted resistin as a potential therapeutic target in sepsis." (PMID 33132754, 2020). "Immunosuppression is central to sepsis-related morbidity and mortality, and resistin (RETN) appears to be a key mediator within this process." (PMID 31147868, 2019). "We found that certain levels of resistin on the first day can be used as a predictor of sepsis in neonates and children." (PMID 31555623, 2019). "Here, we offer further evidence that neutrophils exposed to human resistin exhibit impaired bacterial killing, a characteristic feature of sepsis-induced immunosuppression." (PMID 31147868, 2019). "In emergency department patients with sepsis, resistin and NGAL correlated with the expression of the endothelial cell adhesion molecules (VCAM-1, ICAM-1) and were associated with septic shock, but not with mortality." (PMID 30517161, 2018). "Altered circulating levels of insulin, leptin, resistin, and PAI-1 have been previously indicated in acute settings of sepsis and these molecules have been implicated in sepsis pathogenesis." (PMID 29326685, 2017). "Human primary neutrophils were exposed to different clinical strains isolated from severe sepsis/septic shock cases and degranulation was assessed by measurement of the two sepsis-associated factors HBP and resistin." (PMID 26887258, 2016). "Compared with preoperative blood samples, adiponectin was lowered and resistin and leptin elevated in sepsis." (PMID 27601939, 2016). "In line with published data, we found significantly increased leptin, MCP-1, and resistin levels after onset of sepsis." (PMID 27601939, 2016). "Median plasma adiponectin levels were lowered and resistin and leptin levels elevated in sepsis compared with preseptic plasma levels." (PMID 27601939, 2016). "It is claimed that resistin takesrole as an acute phase reactant due to its up-regulationin patients with severe sepsis and septicshock." (PMID 26644849, 2015). "Adiponectin—the prototype of an anti-inflammatory adipokines and the most abundant adipokine—is diminished in sepsis, while the levels of resistin—a protein with proinflammatory properties—are elevated." (PMID 22272381, 2012). "The best studied adipocytokine in critical illness at present is resistin, which was suggested to serve as an acute-phase component as it is strongly upregulated in patients with severe sepsis and septic shock." (PMID 20871818, 2010). "Serum resistin concentrations are elevated in acute inflammation due to sepsis or systemic inflammatory response syndrome (SIRS)." (PMID 19545363, 2009). "In severe sepsis or septic shock resistin concentrations are twice as high as in non-sepsis critically ill patients." (PMID 19545363, 2009). "The clear association between resistin and inflammatory markers also in the non-sepsis patients indicate that resistin is a component of the systemic inflammatory response." (PMID 19545363, 2009). "In these non-sepsis patients, high resistin levels were an adverse prognostic indicator for the ICU as well as overall survival (P = 0.046, Cox regression model)." (PMID 19545363, 2009).
Sepsis (continued). "Both observations, correlations with renal and liver dysfunction, are in agreement with the interpretation of serum resistin as a sensitive indicator of the systemic inflammatory response in sepsis." (PMID 19545363, 2009). "As highlighted, S100A8/A9 and resistin enhances the ability to distinguish sepsis patients from healthy individuals, assess the severity of sepsis, identify the infecting bacterial type, perform immunotyping of sepsis patients, and predict patient survival outcomes." (PMID 40568710, 2025). "Moreover, growing evidence indicates that resistin serves as a key mediator in the immunosuppressive processes of sepsis." (PMID 40568710, 2025). "Moreover, serum S100A8/A9 levels in sepsis patients show a positive correlation with serum resistin levels." (PMID 40568710, 2025). "RETN promotes inflammatory cell activation, disrupts the immune balance, and damages vascular endothelial cells, thereby contributing to the pathogenesis of sepsis." (PMID 40416430, 2025). "It has been hypothesized that RETN is involved in the pathogenesis of sepsis through its promotion of neutrophil-endothelial cell adhesion." (PMID 40599778, 2025). "The serum levels of S100A8/A9 and resistin were increased in sepsis patients upon admission." (PMID 40568710, 2025). "Our findings support the RETN level as a reliable sepsis marker in infants and children." (PMID 40416430, 2025). "Additionally, the predictive ability of S100A8/A9 and resistin for sepsis mortality was evaluated using the area under the receiver operating characteristic curve at ICU admission." (PMID 40568710, 2025). "Interestingly, RETN and CD163 were positively correlated with the risk of sepsis-related death, whereas KLRB1 was negatively correlated with this risk." (PMID 41472734, 2025). "This multidimensional regulatory network may initially present a pro-inflammatory state (dominated by CD27/RETN) in early sepsis, transitioning to immunosuppression (upregulation of KLRB1/CD163) in later stages." (PMID 41472734, 2025). "However, the potential role of RETN as a mediator of endothelial cell activation in clinical cases of sepsis remains unexamined." (PMID 40599778, 2025). "Additionally, the serum resistin levels in sepsis patients infected with G- and G+ bacteria were notably different." (PMID 40568710, 2025). "The SROC curve for RETN levels in the prediction of sepsis revealed a robust predictive ability." (PMID 40416430, 2025). "Given the ongoing worry over mortality in sepsis therapy, comprehending the predictive capacities of serum resistin might provide doctors with a beneficial instrument for assessing risk and making educated decisions in newborn care." (PMID 38562275, 2024). "Finally, it is unclear if resistin plays a role in sepsis through some intermediary factor in the pathway." (PMID 37834432, 2023). "In summary, our findings suggest that resistin may represent a potential drug for sepsis treatment, particularly among critical patients." (PMID 37834432, 2023). "Despite resistin’s integral role in inflammation, little is understood about how human genetics may mediate its impact on the onset or survival of sepsis." (PMID 37834432, 2023). "Notably, we observed that RETN was upregulated in macrophages during sepsis compared with healthy controls." (PMID 37834432, 2023). "Furthermore, in our prior research employing single-cell technology, we discovered that RETN was elevated in monocytes or macrophages of patients with sepsis in comparison to healthy controls (unpublished), supporting previous studies." (PMID 37834432, 2023). "In bulk transcriptome, RETN is also upregulated in sepsis samples compared with healthy controls." (PMID 37834432, 2023). "MR analyses revealed a negative association existed between the expression of resistin, at both gene and protein levels, and the mortality or severity of sepsis patients in ICU." (PMID 37834432, 2023).
Sepsis (continued). "Moreover, RETN was also upregulated in sepsis samples compared to healthy controls in bulk transcriptome data." (PMID 37834432, 2023). "In an observational study, resistin was higher among infants with severe sepsis or those who needed mechanical ventilation, indicating the potential for resistin in the diagnosis and treatment of sepsis." (PMID 37834432, 2023). "Multiple pieces of evidence also suggest that resistin plays a crucial role in sepsis." (PMID 37834432, 2023). "The Acute Physiology and Chronic Health Evaluation (APACHE) II score and the Sequential Organ-Failure Assessment (SOFA) score were also higher in sepsis, and increased serum resistin concentrations seem to resemble a marker of disease severity independent of a SARS-CoV-2 infection." (PMID 37238973, 2023). "However, as the relevance of acute endotoxemia as a model of clinical sepsis has been questioned, our study is the first to report the effect of resistin in a well-established and clinically relevant surgical model of murine abdominal sepsis." (PMID 35286340, 2022). "These encouraging data provided a likely explanation by which elevated resistin concentrations could mediate severe sepsis and shock in vivo." (PMID 35286340, 2022). "Sepsis was also associated with neutropenia at 24 h following surgery, although resistin production did not significantly affect the degree of neutropenia at this time point." (PMID 35286340, 2022). "Confirmation of these findings might also provide an explanation for the clinically observed and concentration-dependent relationship between resistin and organ dysfunction in sepsis." (PMID 35286340, 2022). "We hypothesized that fecal peritonitis and subsequent surgical sepsis would trigger the production of human resistin in transgenic mice expressing this protein." (PMID 35286340, 2022). "This study aimed to evaluate resistin in COVID-19 pathogenesis compared with sepsis." (PMID 35784283, 2022). "The inability of the scientific community to decipher a consistent role of human resistin in sepsis since its discovery in 2001, beyond that of an inflammatory biomarker like many others, may itself question the clinical relevance of resistin in this disease." (PMID 35286340, 2022). "Furthermore, serum resistin concentrations are elevated in acute inflammation due to sepsis or systemic inflammatory response syndrome (SIRS) in humans." (PMID 35011183, 2021). "These previous findings suggest a paradoxical role for resistin in sepsis." (PMID 33132754, 2020). "In addition, CAP patients without sepsis displayed similar levels of plasma host response biomarkers compared to CAP patients with sepsis, with the exception of modestly higher levels of pentraxin-3, resistin, NGAL and sVCAM-1 in CAP patients with sepsis." (PMID 32477337, 2020). "Our findings demonstrate that resistin selectively and profoundly impairs neutrophil bacterial killing, consistent with the premise that this cytokine alone can reproduce the immunosuppressed cellular phenotype characteristic of sepsis and septic shock." (PMID 31147868, 2019). "We hypothesized that resistin directly contributes to sepsis-induced immunosuppression by selectively targeting the neutrophil component of the innate cellular immune system." (PMID 31147868, 2019). "It has been reported that resistin levels in patients with sepsis alter during an ICU stay." (PMID 31555623, 2019). "While hyperresistinemia (> 20 ng/mL serum RETN concentration) predicts a greater disease severity and a worse prognosis in sepsis, the precise receptor, signaling mechanism, and effects of this cytokine on immune cells remain unknown." (PMID 31147868, 2019). "This correlation may be attributed to the fact that resistin is involved in the release of increased levels of pro-inflammatory biomarkers—IL-6, IL-12 and TNF-ɑ- that are involved in organ failure caused by sepsis." (PMID 30650128, 2019).
Sepsis (continued). "These add up on the established molecules such as Resistin, PAI-1, Adiponectin, Leptin and AGEs (Advanced Glycation End-products) that are prime examples underlying inflammation, putatively accounting for some of the apparent links between sepsis and MetS." (PMID 29922126, 2018). "The plasma resistin elevation in PUUV infection could be a sign of inflammation as previously shown in sepsis." (PMID 30517161, 2018). "Neutrophils were identified as a novel dominant source of resistin in sepsis patients." (PMID 26887258, 2016). "Further, resistin and leptin levels are elevated in sepsis following major surgery." (PMID 27601939, 2016). "It is notable that, for both NGAL and resistin, as well as serum concentrations being higher, gene expression was also greater in circulating leukocytes of patients with severe sepsis compared to uncomplicated sepsis." (PMID 25343379, 2014). "Beyond markers of sepsis and inflammation we could demonstrate a strong correlation of serum resistin concentration to various other laboratory parameters." (PMID 19545363, 2009). "For the subgroup of sepsis patients we could demonstrate that resistin is significantly increased in patients with impaired liver function, as evaluated by serum pseudocholinesterase activity and bilirubin concentration, compared with healthy controls." (PMID 19545363, 2009). "Notably, the expression levels of KLRB1, RETN, and CD163 are closely linked to patient prognosis and may serve as potential targets for future sepsis immunotherapy." (PMID 41472734, 2025). "Additionally, resistin levels were markedly increased in sepsis patients (P < 0.001)." (PMID 40568710, 2025). "Hence, our findings offer new insights into the molecular mechanisms underlying COVID-19 and sepsis-induced ARDS and suggest CD3, CD247, CD2, CD40LG MMP-9, LCN2, and RETN as the potential targets for neutrophils in developing novel therapies and diagnostic tools for these diseases." (PMID 37822934, 2023). "Notably, we observed the upregulation of resistin levels in macrophages during sepsis." (PMID 37834432, 2023). "Given the decreases in blood and peritoneal neutrophil concentrations observed at 6 h in resistin-producing septic mice, we investigated bacterial growth and neutrophil reactive oxygen species production at this time point and at 24 h following the onset of sepsis." (PMID 35286340, 2022). "Hierarchical clustering analysis showed that resistin and inflammatory cytokines formed a network that includes interleukin (IL)-6, IL-8, IL-10 and monocyte chemotactic protein 1 (MCP-1) in the acute phase of sepsis and burns and that this network is associated with severity and prognosis." (PMID 35784283, 2022). "Therefore, a role of resistin in the pathophysiology of critical illness and sepsis seemed likely." (PMID 31569348, 2019). "Moreover, patients with sepsis displayed further elevated resistin concentrations compared with non-septic patients, suggesting a link between inflammation and infection and the secretion of resistin in humans." (PMID 31569348, 2019). "Notably, these data were subsequently corroborated by similar findings of different groups, demonstrating that elevated resistin concentrations correlate with disease severity, inflammatory cytokine, lactate levels, and serum creatinine concentrations in patients with severe sepsis and septic shock." (PMID 31569348, 2019). "However, serum resistin concentrations during sepsis/septic shock do not seem to be associated with underlying chronic kidney disease or diabetes mellitus." (PMID 28779451, 2017). "Moreover, resistin could potentially serve as a prognostic biomarker in non-sepsis critically ill patients." (PMID 19545363, 2009). "For the subgroups of sepsis and non-sepsis patients, we could not find an association of resistin levels on admittance with hyperinsulinemia and glucose levels." (PMID 19545363, 2009).